KATNIP (katanin interacting protein)
Description:
May influence the stability of microtubules (MT), possibly through interaction with the MT-severing katanin complex.
Synonyms: KIAA0556; JBTS26
Tractability: Antibody: its Gene Ontology location is reachable by antibodies, with high confidence. PROTAC: ubiquitination databases record sites on it.
Gene: Protein-coding gene on chromosome 16 (27,550,133 to 27,780,371, forward strand). Ensembl gene ENSG00000047578.
Subcellular location: Cytoplasm, cytoskeleton, cilium axoneme; Cytoplasm, cytoskeleton, cilium basal body; Cytoplasm, cytoskeleton
Subcellular location (Human Protein Atlas): Basal body; Nucleoplasm; Centriolar satellite; Primary cilium
Gene Ontology:
Molecular function: intraciliary transport particle B binding; microtubule binding; protein binding; tubulin binding
Biological process: negative regulation of motile cilium assembly
Cellular component: 9+2 motile cilium; ciliary basal body; ciliary base; cilium; extracellular region; axoneme; cytoskeleton
Genetic constraint (gnomAD): Loss-of-function variants: 112 observed, 160.65 expected, observed/expected ratio (o/e) 0.7, 90% interval 0.6 to 0.82. The upper end of that interval is the gene's LOEUF score, 0.82, which puts it in group 3 of 6, group 1 being the genes least tolerant of losing a copy. Missense variants: 1,902 observed, 2,090.2 expected, observed/expected ratio (o/e) 0.91, 90% interval 0.88 to 0.94. Synonymous variants: 777 observed, 835.28 expected, observed/expected ratio (o/e) 0.93, 90% interval 0.88 to 0.99.
Gene-disease validity (ClinGen):
ClinGen rates the evidence that KATNIP causes each of these diseases.
ciliopathy (autosomal recessive): Definitive. A genetic disorder of the cellular cilia or the cilia anchoring structures, the basal bodies, or of ciliary function.
Homologues: Orthologues: chimpanzee KATNIP (99% identical), macaque KATNIP (95% identical), pig KATNIP (79% identical), guinea pig KATNIP (73% identical), rabbit KATNIP (73% identical), rat Katnip (73% identical), mouse Katnip (72% identical), dog KATNIP (71% identical), tropical clawed frog katnip (44% identical), zebrafish katnip (13% identical), zebrafish si:dkey-161j23.7 (13% identical), zebrafish si:dkey-161j23.5 (11% identical), and 1 more.
Diseases named in the same sentence as KATNIP in open-access papers:
KATNIP is named in the same sentence as 28 diseases in open-access papers, as found by Europe PMC text mining. Sharing a sentence is not in itself a finding about the gene and the disease. The quoted sentences say what the papers report.
Joubert syndrome (10 papers, 2015 to 2025). Joubert syndrome (JS) is characterized by congenital malformation of the brainstem and agenesis or hypoplasia of the cerebellar vermis leading to an abnormal respiratory pattern, nystagmus, hypotonia, ataxia, and delay in achieving motor milestones. "Novel genotype–phenotype correlations included biallelic pathogenic variants in KATNIP, previously associated with Joubert syndrome (JBTS), in an individual who presented with kidney disease and IRD, but no other features of JBTS." (PMID 40725402, 2025). "KATNIP pathogenic variants represent a rare cause of JS (Joubert Syndrome 26 OMIM #616784)." (PMID 40428346, 2025). "We suspect inadequate phenotyping may also play a role in explaining the presence of homozygotes for some pathogenic variants in gnomAD e.g. there is a homozygote in gnomAD for the pathogenic stopgain variant we identified in KATNIP in family F6141 with classical Joubert syndrome." (PMID 37644014, 2023).
ciliopathy (4 papers, 2020 to 2025). "Nevertheless, we provide further evidence that ciliopathies contribute to esophageal atresia and identify KATNIP variants as an EA/TEF possible predisposing factor." (PMID 40428346, 2025). "Polydactyly, which is frequent in JS and a classical “ciliopathy” feature, was never reported before in individuals with KATNIP variants." (PMID 40428346, 2025).
anemia (1 paper, 2025). A reduction in the number of red blood cells, the amount of hemoglobin, and/or the volume of packed red blood cells. "He did not have MTS, but showed severe anemia and esophageal atresia, which was already reported in association with a KATNIP variant." (PMID 40428346, 2025).
developmental delay (1 paper, 2025). "Pathogenic variants in KATNIP have been associated with JBTS, a severe phenotype compatible with retinal degeneration and kidney disease, and usually involving developmental delay and intellectual disability." (PMID 40725402, 2025).
kidney disease (1 paper, 2025). "Renal disease was not previously reported in individuals with KATNIP pathogenic variants." (PMID 40725402, 2025).
KATNIP also shares sentences with these, for which no sentence is quoted: tumor (2 papers); adenoma (1); Bardet-Biedl syndrome (1); cancer (1); Central hypothyroidism (1); cleft lip (1); colorectal cancer (1); communicating hydrocephalus (1); cystic kidney disease (1); entropion (1); epilepsy (1); Esophageal atresia (1); hearing loss (1); Hydrocephalus (1); Infertility (1); Intellectual disability (1); neurological disorder (1); ocular coloboma (1); oral cancer (1); polydactyly (1); ptosis (1); retinal degeneration (1); Rod-cone dystrophy (1).